EWSR1 (EWS RNA binding protein 1)
Diseases named in the same sentence as EWSR1 in open-access papers (continued):
Sharing a sentence is not in itself a finding about the gene and the disease.
clear cell sarcoma (continued). "However, analysis by fluorescence in situ hybridization (FISH) found a rearrangement of the Ewing sarcoma region 1 (EWSR1) gene, which led to a diagnosis of primary clear cell sarcoma in the skin." (PMID 36589177, 2022). "However, EWSR1 gene abnormalities are unspecific as they are found in many other tumors such as clear cell sarcoma, extraskeletal myxoid chondrosarcoma, round-cell myxoid liposarcoma, and myoepithelial carcinoma." (PMID 36164527, 2022). "Based on our preclinical findings, indicating a major role of CREB in SySa tumorigenesis, these rare mesenchymal tumors appear to functionally join clear cell sarcoma, in which EWSR1-CREB or EWSR1-ATF1 gene fusions drive sarcomagenesis, directly involving CREB within the fusion protein." (PMID 35556229, 2022). "Finally, another fusion transcript, EWSR1/CREB1, has been implicated in upregulation of MET oncogene in clear-cell sarcoma." (PMID 23329308, 2013). "These two forms of HEY1::NCOA2 fusion might be caused by splicing alterations, as an EWSR1::ATF1 fusion was identified in clear cell sarcoma, although we do not have any data." (PMID 39165647, 2024). "Furthermore, dual-color, break-apart FISH using break-apart rearrangement specific for EWSR1 gene on 22q13 is usually used for distinguishes clear cell sarcoma of soft tissue from melanoma, but using the probe does not suggest fusion types or breakpoints of EWS gene rearrangement." (PMID 33478436, 2021). "Fusions involving EWSR1 occur in other tumors, including desmoplastic small round cell tumor (EWSR1-WT1), clear cell sarcoma (EWSR1-ATF1), myxoid liposarcoma, extra-skeletal myxoid chondrosarcoma, and rare CNS tumors." (PMID 41301081, 2025). "RT-PCR is recommended to confirm the gene fusion.8) However, the fusion of EWSR1 with CREB1 itself has also been reported in other tumors such as hemangioma-like fibrous histiocytomas and soft tissue clear cell sarcomas." (PMID 40242429, 2025). "Although EWSR1::ATF1 and FUS::ATF1 fusions are reported in clear-cell sarcomas and AFH,25,26 the cases herein with EWSR1/FUS::ATF1 fusions were very close to the AFH cluster, but clearly separated on the UMAP projection." (PMID 39059063, 2024). "We have recently demonstrated that the use of human embryonic stem mesenchymal progenitors (hES-MP) is important in the generation of Clear Cell Sarcoma (CCS) and Angiomatoid Fibrous Histiocytoma (AFH) models harboring the EWSR1::ATF1/CREB1 translocations." (PMID 36801905, 2023). "No deletion or amplification of EWSR1 locus was found in any of the clear cell sarcoma cases assessed." (PMID 40666501, 2025). "As yet, the function of CREB in SySa has not been evaluated, but pathogenic translocations between EWSR1 and CREB or its homologue ATF1 in clear cell sarcoma, another fusion-driven mesenchymal neoplasia, point to a major functional role in mesenchymal tumorigenesis." (PMID 35556229, 2022). "However gastrointestinal clear cell sarcomas are usually negative for epithelial markers and show rearrangement of the EWSR1 gene." (PMID 25699170, 2015). "However, clear cell sarcoma is genetically distinct lacking melanoma-associated BRAF mutations and instead harboring recurrent and characteristic chromosomal translocations involving the EWSR1 gene." (PMID 22693489, 2012). "Clear cell sarcoma (CCS), a rare but extremely aggressive malignancy with no effective therapy, is characterized by the expression of the oncogenic driver fusion gene EWSR1::ATF1." (PMID 37405123, 2023). "Interestingly, we noted that EWSR1::ATF1 oncoprotein interacted with MS0621, whereas native ATF1 did not in non-clear cell sarcoma cells." (PMID 36793594, 2023).
rhabdomyosarcoma (41 papers, 1999 to 2026). A rare aggressive malignant mesenchymal neoplasm arising from skeletal muscle. "The translocation of TFCP2 (usually exon 2) with either FET family member—EWSR1 (usually exon 5) or FUS (usually exon 6)—most often results in an epithelioid variant of rhabdomyosarcoma." (PMID 40361368, 2025). "Similar to PAX3-FOXO1 in rhabdomyosarcoma and EWSR1-associated fusions in Ewing sarcoma, our data indicate a substantial co-localization of BRD4 and FUS-DDIT3, and a BET protein-dependent function of FUS-DDIT3 via physical interaction in MLPS." (PMID 30903020, 2019). "Background/Objectives: The fusion of the TFCP2 gene with either EWSR1 or FUS typically results in a spindle cell and/or epithelioid variant of rhabdomyosarcoma." (PMID 40361368, 2025). "Rhabdomyosarcoma with TFCP2 rearrangement (TFCP2-RMS) is a high-grade rhabdomyosarcoma, characterized by a fusion of TFCP2 to EWSR-1 or FUS." (PMID 35059992, 2022).
desmoplastic small round cell tumor (39 papers, 2008 to 2026). Desmoplastic small round cell tumor (DSRCT) is an aggressive soft tissue cancer that typically arises in serous lined surfaces of the abdominal or pelvic peritoneum, and spreads to the omentum, lymph nodes and hematogenously disseminates especially to the liver. "Desmoplastic Small Round Cell Tumor (DSRCT) is a highly aggressive pediatric cancer caused by a reciprocal translocation between chromosomes 11 and 22, leading to the formation of the EWSR1::WT1 oncoprotein." (PMID 39139449, 2024). "Desmoplastic small round cell tumours (DSRCTs) represent an ultra-rare subtype of soft tissue sarcoma characterized by a recurrent EWSR1::WT1 oncogenic translocation." (PMID 39921935, 2025). "Desmoplastic Small Round Cell Tumor (DSRCT) is a rare, pediatric cancer caused by the EWSR1::WT1 fusion protein." (PMID 38575753, 2024). "Desmoplastic Small Round Cell Tumor (DSRCT) is a rare, pediatric cancer caused by the EWSR1::WT1 fusion protein, which alters transcription and drives oncogenesis." (PMID 38575753, 2024). "As EWSR1 rearrangement may be found in other tumors such as desmoplastic small round cell tumors, a detection of fusion types (EWSR1/FLI-1 and EWSR1/ERG) from RNA is necessary to confirm the diagnosis using reverse transcription polymerase chain reaction (RT-PCR), which is a highly specific method." (PMID 30319719, 2018). "Desmoplastic small round cell tumor (DSRCT) is a rare and aggressive mesenchymal tumor characterized by the expression of the EWSR1::WT1 fusion." (PMID 40852926, 2025). "Subsequent studies showed that EWSR1 is fused to various types of transcription factors in multiple sarcomas (e.g., EWSR1-WT1; desmoplastic small round cell tumor, EWSR1-ATF1;clear cell sarcoma, EWSR1-CHOP; myxoid liposarcoma, EWSR1-NR4A3; extraskeletal myxoid chondrosarcoma)." (PMID 36875767, 2023). "Desmoplastic small round cell tumor (DSRCT), an aggressive primitive tumor of children and young adults, particularly males, is also characterized by a recurrent translocation involving the EWSR1 gene." (PMID 29455671, 2018).
neuroblastoma (35 papers, 1999 to 2026). Neuroblastoma (NB) is the most common solid, extracranial childhood tumor. "This mode is also illustrated by circCUX1, which promotes aerobic glycolysis and neuroblastoma progression by strengthening the transactivation of MYC-associated zinc finger protein (MAZ) by EWS RNA binding protein 1 (EWSR1)." (PMID 33317550, 2020). "For example, CUT-like homeobox 1 (CUX1)-generated circular RNA (circ-CUX1) enhances the trans-activation of MYC-associated zinc finger protein (MAZ) through EWS RNA-binding protein 1 (EWSR1), thereby promoting aerobic glycolysis and neuroblastoma progression." (PMID 39062737, 2024). "Circ‐CUX1 binds to the RRM region of EWSR1 and promotes MAZ transactivation, thereby altering the transcription of CUX1 and the association of other genes with neuroblastoma progression." (PMID 35592755, 2022). "circ-CUX1 binds to Ewing Sarcoma (EWS) RBP1 (EWSR1), resulting in transactivation of MYC-associated zinc finger protein (MAZ) and inhibiting glycolysis to suppress the progression of neuroblastoma." (PMID 33425493, 2021). "For example, circCUX1 binds with EWS RNA-binding protein 1 (EWSR1) to promote its interplay with MAZ (MYC-associated zinc finger protein), glycolysis and neuroblastoma progression." (PMID 34116677, 2021). "The circ‐CUX1/EWSR1/MAZ axis emerges as a possible therapeutic target for neuroblastoma progression." (PMID 31709724, 2019). "This frontal lobe tumor, which histologically intermingled with the neuropil andcontained a mixture of areas recognizable as schwannoma and others of primitiveappearance reminiscent of neuroblastoma, was only correctly diagnosed following thedemonstration of an EWSR1::VGLL1 fusion." (PMID 41522855, 2026). "Using EIP-22, the researchers discovered that EWSR1 could prevent circCUX1-EWSR1 connections from reducing the development and migration of neuroblastoma SH-SY5Y cells." (PMID 37091173, 2023). "In addition, circCUX1 binds to EWS RNA-binding protein 1 to facilitate its interaction with MYC-associated zinc finger protein, resulting in neuroblastoma progression." (PMID 33741902, 2021). "circCUX1 interacted with EWS RNA-binding protein 1 (EWSR1) and facilitated EWSR1-mediated transactivation of MYC-associated zinc finger protein (MAZ), promoting the transcriptional of CUX1, glycolysis and neuroblastoma progression." (PMID 33643900, 2020). "circCUX1 interacted with EWSR1 and facilitated EWSR1-mediated MYC-associated zinc finger protein (MAZ) transactivation, resulting in transcriptional activation of its host gene CUX1 in neuroblastoma." (PMID 33537235, 2020). "Knockdown of EWSR1 inhibited the oncogenic potential of neuroblastoma cell lines." (PMID 29212266, 2017). "While EWS-FLI1 fusion protein is not frequently found in NB, using the R2 public database of neuroblastoma outcome and gene expression, we found that high expression of EWSR1 was associated with poor patient outcome." (PMID 29212266, 2017). "This suggests the circCUX1/EWSR1/MAZ axis can be a therapeutic target for aerobic glycolysis and neuroblastoma progression." (PMID 35592755, 2022). "It has been reported that circ-CUX1 binds to EWSR1 and transactivates MAZ, which contributes to aerobic glycolysis and the progression of neuroblastoma." (PMID 33425493, 2021). "Li H’s team identified that circ-CUX1 bonded to EWS RNA-binding protein 1 (EWSR1) to expedite its interacting process with MYC-related zinc finger protein (MAZ), thus leading to promotion of aerobic glycolysis and tumor progression in neuroblastoma." (PMID 32665846, 2020). "Similarly, circ-CUX1 binds to EWS RNA-binding protein 1 (EWSR1) to promote its interaction with MYC-associated zinc finger protein (MAZ), transactivating MAZ, and modulating CUX1 expression to facilitate the metabolic reprogramming and progression of neuroblastoma (NB)." (PMID 36186139, 2022).
melanoma (34 papers, 2003 to 2025). A malignant, usually aggressive tumor composed of atypical, neoplastic melanocytes. "In conclusion, our results from the melanoma cell line CHL-1 confirm that EWSR1::CREM is an oncogenic fusion protein with cell cycle accelerating properties leading to increased proliferation, increased migration and evasion of senescence." (PMID 36966162, 2023). "The antibody readily detected an EWSR1-CREM fusion protein in Western blotting of a melanoma cell line, and IHC in an MEC with EWSR1-CREM fusion gene was positive." (PMID 34261344, 2021). "To explore an oncogenic contribution of EWSR1/CREM in melanoma, we again used RNAi to knockdown expression of the fusion." (PMID 23637631, 2013). "However, CCS has a distinct cytogenetic profile, particularly the EWSR1 gene rearrangement, which differentiates it from melanoma and contributes to its unique clinical course." (PMID 40260360, 2025). "BRAF mutations are observed in about 52% of malignant melanoma cases, but EWSR1 rearrangement has not been identified in malignant melanoma." (PMID 32316685, 2020). "Breakpoint analysis also identified a novel EWSR1/CREM fusion in melanoma (CHL-1)." (PMID 23637631, 2013). "Thus, EWSR1/CREM potentially represents the first oncogenic gene fusion discovered to date in melanoma." (PMID 23637631, 2013). "In this study, we performed transcriptional profiling of the melanoma cell line CHL-1, with depletion of endogenous EWSR1::CREM protein using siRNA mediated knockdown." (PMID 36966162, 2023). "Despite its similarity with melanoma, CCS is a distinct entity genetically characterized by the presence of a chromosomal translocation involving EWSR1 most frequently partnered with ATF1." (PMID 20598147, 2010). "However, it is genetically distinct, lacking melanoma-associated BRAF mutations and instead featuring recurrent and characteristic chromosomal translocations involving the EWSR1 gene." (PMID 40260360, 2025). "This specific rearrangement of the EWSR1/ATF1 genes serves as a defining genetic feature of CCSST, setting it apart from malignant melanoma, where such rearrangement is notably absent." (PMID 38755643, 2024).
osteosarcoma (32 papers, 2011 to 2026). A usually aggressive malignant bone-forming mesenchymal neoplasm, predominantly affecting adolescents and young adults. "In accordance, EWSR1-ETS associated DSBs have been identified and radiation induced damage turnover in EWS was reduced compared to osteosarcoma." (PMID 26193259, 2015). "However, NGS revealed a complex genome lacking the characteristic EWSR1-associated rearrangements and instead identified deletions in RB1, PTCH1, and ATRX, confirming the diagnosis of osteosarcoma." (PMID 40115314, 2025). "Unlike the more common osteosarcoma, ES cells have a genomic translocation giving rise to well characterised mutant fusion genes such as EWSR1-FLI1 or EWSR1-ERG, which primarily drive the disease." (PMID 33669307, 2021).
bone tumor (31 papers, 2003 to 2026). "According to the WHO classification of bone tumors (2020), EWS is categorized as a small round cell sarcoma, primarily characterized by different EWS gene (EWSR1) fusions on chromosome 22q12." (PMID 40823187, 2025). "Combined, these data indicate that EWSR1-rearrangements are rare in malignant bone tumors showing myoepithelial differentiation." (PMID 22588017, 2011). "Among the nine bone cancer samples examined, three fusions involving EWSR1 were identified." (PMID 38800398, 2024). "Furthermore, pediatric cancers tend to have fewer somatic mutations with many of them driven by single chromosomal translocation events such as the PAX3–FOXO1 fusion in RMS or EWSR1 fusions in various soft tissue and bone tumors." (PMID 36346688, 2023). "An EWSR1/POU5F1, EWSR1/PBX1 or EWSR1/ZNF444 fusion gene, or a rearrangement of the EWSR1 gene with unknown fusion partner, was detected in close to half of the soft tissue lesions, and in four out of five bone tumors." (PMID 22588017, 2011). "However, all EWSR1-positive bone tumors were classified as benign; the single malignant myoepithelial tumor of bone was negative." (PMID 22588017, 2011). "These four gene-cancer pairs were EWSR1 (26.3% vs. 13.0%) and FLI1 in bone cancer (23.2% vs. 9.6%), BRAF in glioma (3.6% vs. 0.4%), and TEF3 in renal cell carcinoma (8.5% vs. 1.7%)." (PMID 36433963, 2022).
mesenchymal neoplasms (30 papers, 2014 to 2025). "Rearrangements between EWSR1 and other genes lead to the formation of hybrid proteins with oncogenic potential associated with neoplastic cell ­transformation, both in the mesenchymal neoplasms and in other cancer models." (PMID 34374640, 2022). "The spectrum of mesenchymal tumors associated with rearrangements of the EWSR1 gene has been growing in recent years due to progress in molecular detection techniques." (PMID 31049020, 2019). "Based on these findings, the tumor was diagnosed as an epithelioid mesenchymal tumor with EWSR1::CREM gene fusion." (PMID 40242428, 2025). "Myoepithelial tumor of soft tissue is a rare mesenchymal tumor with characteristic gene fusion involving the EWSR1 or FUS gene in about 50% of cases." (PMID 40978976, 2025). "Based on a pathology consultation, the tumor was diagnosed as a mesenchymal tumor with EWSR1::CREM fusion." (PMID 40242428, 2025). "Myoepithelial tumors of soft tissue are mesenchymal tumors with characteristic gene fusions involving the EWSR1 or FUS gene in many cases." (PMID 40978976, 2025). "Early descriptions of EWSR1::NFATC2-rearranged mesenchymal neoplasms placed them in the category of Ewing-like undifferentiated round cell sarcoma." (PMID 39636306, 2025). "Here, we report our experience with a gastric mesenchymal tumor with epithelioid histology and an EWSR1::CREM fusion, which is rare but requires caution." (PMID 40242428, 2025). "The majority of translocations involving EWSR1 gene in mesenchymal neoplasms are balanced translocations." (PMID 40666501, 2025). "Including our study, 10 unclassified mesenchymal neoplasms with epithelioid/round cell morphology and an EWSR1::ATF1 fusion have been reported." (PMID 39031200, 2024). "EWSR1 is a ‘promiscuous’ gene that can fuse with many different partner genes, defining different entities among a broad range of mesenchymal neoplasms." (PMID 38339014, 2024). "Herein, we report three cases with rare GFs involving EWSR1 in undifferentiated mesenchymal neoplasms with uncertain differential diagnoses, using targeted RNA-seq and confirming with RT-PCR and Sanger sequencing." (PMID 38339014, 2024). "In conclusion, our findings indicate that the catalogue of mesenchymal neoplasm-bearing EWSR1 fusions continues to grow, underscoring the value of using molecular ancillary techniques with higher diagnostic abilities in the routine clinical setting." (PMID 38339014, 2024). "EWSR1 rearrangement represents one of the most frequent molecular events in mesenchymal neoplasm, and a rare genetic event, that has an increasing number of reported cases, in non-mesenchymal tumors." (PMID 34374640, 2022). "All these observations underline the morphological and immunophenotypic heterogeneity of EWSR1/FUS-CREM fusion driven mesenchymal neoplasms." (PMID 34228212, 2022). "EWSR1-CREM fusion genes have been found in several mesenchymal tumors and in salivary gland carcinoma." (PMID 34261344, 2021). "Recently, cases of intracranial myxoid mesenchymal neoplasms harboring EWSR1-CREB family gene fusions have been reported in young patients with histologic features reminiscent of the myxoid variant of angiomatoid fibrous histiocytoma." (PMID 33738448, 2021). "We present 2 cases of intracranial myxoid mesenchymal tumor with EWSR1-CREB gene fusion who have long-term follow-up currently demonstrating an absence of progression in both, one of which in response to targeted crizotinib monotherapy." (PMID 33738448, 2021). "EWSR1 is well-known to be able to fuse with a range of genes in the mesenchymal neoplasms, and a few series of epithelial tumors as myoepithelial, primary clear cell carcinoma of the thymus and the Xp11 translocation renal cell carcinoma." (PMID 34612781, 2021). "The EWSR1 was the first gene identified in relation to the pathogenesis of a mesenchymal tumor in the early 90s." (PMID 31049020, 2019).